CLCA2 (chloride channel accessory 2)
Diseases named in the same sentence as CLCA2 in open-access papers (continued):
Sharing a sentence is not in itself a finding about the gene and the disease.
myocardial infarction (2 papers, 2021). Gross necrosis of the myocardium, as a result of interruption of the blood supply to the area, as in coronary thrombosis. "Our data suggest that CLCA2 expression is stimulated by myocardial infarction and is sensitive both to fetal dECM factors and tissue stiffness." (PMID 34805326, 2021). "In order to compare Clca2 expression in quiescent cardiac fibroblasts and activated cardiac fibroblasts, C57B/6 mice were subjected to the LAD procedure to induce myocardial infarction; previous investigations have shown that FMyT peaks at 7 day after the surgery." (PMID 34869368, 2021). "Myocardial infarction did not significantly change CLCA2 expression though it was interest for the inverse response to the dECM treatments and potential mechano-signaling." (PMID 34805326, 2021).
squamous cell carcinoma (2 papers, 2014 to 2024). A carcinoma arising from squamous epithelial cells. "In this research, in squamous cell carcinoma histology, survivin was most commonly expressed in 55% of patients, followed by CLCA2 and CK7 in 45% of patients each." (PMID 39130876, 2024). "The low CLCA2 expression level in the normal lung suggests that the role of CLCA2 in the noncancerous lung tissue might not be greater than that in patients with squamous cell carcinoma of the lung." (PMID 25548429, 2014).
cardiac conduction defect (1 paper, 2018). "Moreover, a CLCA2 mutation was recently found to cause a familial heart disease, Progressive Cardiac Conduction Defect." (PMID 29758025, 2018).
colon cancer (1 paper, 2016). "Moreover, the CLCA2 gene has been shown to act as a tumor suppressor in breast and colon cancer, where it is often decreased." (PMID 27081700, 2016).
colorectal tumours (1 paper, 2010). "In contrast, the expression of two other chloride channels (the Ca2+-dependent chloride channels CLCA1 and CLCA2) was downregulated in 80% of colorectal tumours, although the biological significance of this repression remains to be determined." (PMID 20087350, 2010).
Hallux valgus (1 paper, 2020). Lateral deviation of the great toe (i.e., in the direction of the little toe). "Functional annotation of hallux valgus associated variants in CLCA2 revealed that rs55807512 is among the top (< 10%) of deleterious mutations in the genome (CADD = 11.89)." (PMID 32131869, 2020). "The lead variant, rs55807512, located in an intronic region of chromosome 1 within CLCA2 gene, had MAF around 4% and was not included in the first hallux valgus GWAS." (PMID 32131869, 2020).
Immunodeficiency (1 paper, 2006). Failure of the immune system to protect the body adequately from infection, due to the absence or insufficiency of some component process or substance. "Our data also supports the fact that immunodeficiency is correlated with altered calcium ion binding (UTRN, ID: AA676840; CDH6, ID: AA421819, CASQ2, ID: AA055163) and also is influenced by calcium- activated chloride channels (CLCA2, ID: AI675394) of host cells." (PMID 16956415, 2006).
metastatic tumors (1 paper, 2018). "Overexpression of CLCA2 inhibited NPC cell migration and invasion, and overexpression of CLCA2 resulted in fewer pulmonary metastatic tumors in nude mice." (PMID 29463274, 2018).
non-small cell lung carcinoma (1 paper, 2006). A group of at least three distinct histological types of lung cancer, including non-small cell squamous cell carcinoma, adenocarcinoma, and large cell carcinoma. "CLCA2 belongs to calcium sensitive chloride conductance protein family and has been used in a multigene detection assay for Non Small Cell Lung Cancer (NSCLC)." (PMID 17217525, 2006).
Osteochondrosis (1 paper, 2020). Abnormal growth ossification centers in children. "Although another member of CLCA family, CLCA4, has been reported to be associated with osteochondrosis in the horse, CLCA2 has not been associated with bone formation or any musculoskeletal disorders." (PMID 32131869, 2020).
ovarian carcinoma (1 paper, 2022). A malignant neoplasm originating from the surface ovarian epithelium. "It is reported that NDRG1 gene may play an important role in the invasion and metastasis of cervical and ovarian cancer through its downstream CLCA2 gene." (PMID 36280802, 2022).
skin aging (1 paper, 2024). The gradual irreversible changes in structure of skin that occur as a result of the passage of time.. "To explore the role of CLCA2 in the context of skin aging, we employed 3D skin equivalent (SE) models." (PMID 38540205, 2024).
tumor (34 papers, 2007 to 2025). "Several subunits are upregulated (e.g. Cavβ, Cavγ) and downregulated (e.g. Kvβ) in cancer, while other subunits have been functionally implicated as oncogenes (e.g. Navβ1, Cavα2δ1) and tumour suppressor genes (e.g. CLCA2, KCNE2, BKγ1) based on in vivo studies." (PMID 31071485, 2019). "Up-regulation of ROCK1 and TPR and down-regulation of ALDH4A1 and CLCA2 are positively associated with the processes of migration, metastasis, and invasion of tumor cells and negatively associated with proliferation." (PMID 31438847, 2019). "CLCA2 is required for epithelial differentiation, and its loss during tumor progression contributes to metastasis." (PMID 23593331, 2013). "The CLCA2 protein expression status was associated with the histological tumor grade in the SCCs." (PMID 25548429, 2014). "A deeper analysis revealed upregulation of genes involved in tumor suppression (Clca2, Spink5, Igfbp6, Nptx1, Bex4, Gadd45g, Yipf5), immune regulation (IL6ra, Ccl6, Cd81, Cd244a, Cd151, and Gata4), apoptosis, and pyroptosis (Ddit3, Rgs6, and Gsdmsc2/3/4)." (PMID 39946195, 2025). "Consistent with previous observations, CLCA2 overexpression led to a obvious reduction in tumor volume." (PMID 36280802, 2022). "Among the up-regulated genes in Luminal-Basal-type (vs. both Basal-single-type and Luminal-single-type) were present MUCL1, a known tumor suppressor gene, and CLCA2, a negative regulator of cancer cell migration and invasion." (PMID 35984580, 2022). "Alterations in the Ca channel (activated chloride channel-2, CLCA2) were also detected in RT-PCR with circulating tumor cells (CTC) in patients with lung AC39." (PMID 32587780, 2020). "Tumor cell lines that upregulate CLCA2 also upregulate TMEM16A and EGFR, suggesting TMEM16A and CLCA2 are part of an EGFR-promoting axis." (PMID 32575848, 2020). "CLCA2 overexpression suppressed xenograft tumor growth and lung, popliteal lymph node (LN) metastasis in vivo." (PMID 29463274, 2018). "It is a novel self-cleaving extracellular metalloprotease and is a homologue of likely tumor suppressors, CLCA2 and CLCA4." (PMID 29515771, 2018). "CLCA2 inhibited tumor metastasis through suppressing epithelial-Mesenchymal transition (EMT) and in-activating FAK/ERK1/2 signaling pathway in NPC cells." (PMID 29463274, 2018). "Taken together, These results strongly suggest that CLCA2 acts as a tumor suppressor in the development of NPC." (PMID 29463274, 2018). "Using the Oncomine database, CLCA2 expression was found to be markedly decreased in primary tumor tissues of the lung, prostate and bladder." (PMID 29463274, 2018). "Both are precipitously downregulated with tumor progression (it should be noted that CLCA4 was misidentified as CLCA2 in that study)." (PMID 24386311, 2013). "We found previously that the candidate tumor suppressor CLCA2 is expressed in differentiated, growth-arrested mammary epithelial cells but is downregulated during tumor progression and EMT." (PMID 24386311, 2013). "Previous studies have shown that CLCA2 participates in cell proliferation, DNA damage, stress, apoptosis, adhesion, and invasion, and thus participates in regulating inflammation and tumor progression." (PMID 38528613, 2024). "TMEM16A and CLCA2 are upregulated in some tumours, which may lead to enhancement of TMEM16A currents and tumour progression." (PMID 35163502, 2022). "Finally, overexpression of CLCA2 remarkably inhibited tumor growth after tumor formation compared with control group." (PMID 29463274, 2018).
tumor (continued). "The frequent loss of CLCA4 expression with tumor progression suggested that CLCA4, like CLCA2, might antagonize tumorigenesis." (PMID 24386311, 2013). "Similarly, increased CLCA2 expression is seen in circulating lung adenocarcinoma cells and ovarian cancer cell aggregates, suggesting CLCAs may potentially be tumour suppressors on the one hand, and metastasis-promoting on the other." (PMID 31071485, 2019). "In addition, inhibition of FAK and ERK1/2 reversed CLCA2 silencing-induced tumor cell migration." (PMID 29463274, 2018). "Future studies to identify other binding partners at cell-cell junctions and functional studies of the role of CLCA2 metalloprotease activity on the organization of lateral junctions may reveal new tumor suppressive pathways that can be exploited in cancer prevention or therapy." (PMID 26930581, 2016). "Other signature genes (TP63, CERS3, CSTA, CLCA2, DSC3 and DSG3) upregulated in C1 tumours are also markers of the squamous-like subtype, while further columnar-like marker genes (MUC5B and RGL3) are upregulated in C2 tumours." (PMID 36207323, 2022). "We found that the lymph node metastasis rate was significantly reduced from 61% (22/36) to 35% (12/37) via overexpression of CLCA2 in NPC cells, but the primary tumor weight in the left hind footpad remained similar." (PMID 29463274, 2018). "CLCA2 in growth and metastasis of NPC were evaluated in vivo through NPC xenograft tumor growth, lung metastatic mice model and popliteal lymph node (LN) metastasis model." (PMID 29463274, 2018). "A six-fold increase in mRNA expression was observed in tumor samples of CL, CLCA1 and CLCA2 groups relative to the NC group." (PMID 21811552, 2011). "All the tumor biopsies of animals inoculated with ACP03 (CL, CLCA1 and CLCA2 groups) presented MYC protein overexpression." (PMID 21811552, 2011). "The tumor volumes of CL, CLCA1, and CLCA2 groups were similar and all animals were able to eliminate the tumors." (PMID 21811552, 2011). "At the cellular level, CLCA2 inhibits the WNT signaling pathway or the ERK/JNK/p38-MAPK pathway to suppress epithelial-mesenchymal transition (EMT), thereby impeding tumor metastasis." (PMID 38528613, 2024). "In addition, some reports have revealed involvement of CLCA1, CLCA2, and CLCA4 in tumor progression." (PMID 29190973, 2017). "CLCA2 and ANO1 may be used already today as markers for circulating cancer cells to monitor efficacy of the therapy directed against the primary tumor or to estimate the systemic cancer cell burden." (PMID 27618016, 2016). "However, CLCA2 is an important component of the calcium-activated chloride channel (CACC) family, which regulates ion homeostasis, maintains a stable intracellular pH, changes the pH environment of tumor cells, and inhibits cancer progression." (PMID 38528613, 2024). "We also did not observe differences in the tumor volume among CL, CLCA1 and CLCA2 groups." (PMID 21811552, 2011).
cancer (27 papers, 2010 to 2025). A tumor composed of atypical neoplastic, often pleomorphic cells that invade other tissues. "The volcano plot further confirmed the importance of these genes by pinpointing significantly upregulated and downregulated genes, such as TP63, NTRK2, and CLCA2, which are strongly associated with cancer." (PMID 40370696, 2025). "Despite this in vitro evidence for a favorable prognostic role of CLCA2 in cancers, very few studies have been reported associations between CLCA2 expression in cancer with respect to clinical outcomes in humans." (PMID 32298355, 2020). "Thus, in addition to the effects on epithelial differentiation, the loss of EVA1 and/or CLCA2 in breast epithelium might impair immunosurveillance that normally suppresses cancer emergence." (PMID 26930581, 2016). "Thus, acquisition of survival advantage of cancer cells associated with downregulation of CLCA2 might be one of the reasons why reduced CLCA2 expression leads to a poor survival outcome in patients with lung SCC." (PMID 25548429, 2014). "Red dots denote significantly upregulated genes, such as TP63, NTRK2, and CLCA2, highlighting their elevated expression in cancer samples." (PMID 40370696, 2025). "CLCA2 is a chloride ion channel regulator involved in cancer cell adhesion, migration, and proliferation." (PMID 34805326, 2021). "Inhibition of CLCA2 stimulates cancer cell migration and invasion." (PMID 31438847, 2019). "CLCA2 on the other hand is better known for its role in cancer." (PMID 29758025, 2018). "CLCA1, CLCA2, and CLCA4 have all been implicated in various cancers as have a number of TMEM16 proteins, and such studies could have tremendous implications for cooperative CLCA/TMEM16 roles in cancer and other diseases." (PMID 25781344, 2015). "CLCA2 immunoreactivity was observed in the cytoplasm and membrane of the cancer cells, and calculation of the immunohistochemical score revealed that it was significantly higher in the SCCs than in the ADCs (median, 170 versus 0; P < 0.0001, Mann-Whitney U test)." (PMID 25548429, 2014). "Moreover, CLCA2 expression is usually downregulated in cancer cells." (PMID 33271924, 2020). "Analysis of patient data revealed a prognostic and predictive value of CLCA2 and ANO1 mRNA abundance in CTCs for lung and gastrointestinal cancer, respectively." (PMID 27618016, 2016). "Knocking out CLCA2 gene will induce EMT and increase the invasiveness of cancer cells." (PMID 36280802, 2022). "Furthermore, we found that overexpression of CLCA2 inhibits NPC growth and metastasis in vitro and in vivo, and knockdown of CLCA2 by siRNA promotes NPC cell migration and invasion though activation of FAK, which is a key driving force in cancer progression." (PMID 29463274, 2018). "The ability of CLCA2 to inhibit cancer cell migration appears to be ICl independent, as inhibiting ICl has a further anti-migratory effect in cells expressing CLCA2 as well as having an anti-migratory effect in cells not expressing CLCA2." (PMID 31071485, 2019).
cancer (continued). "As CLCA2 is not sufficiently expressed in cell line LNZ308 with a log-expression of −5.8 in the Cancer Cell Line Encyclopedia data, we stimulate cell lines SF767 and LNZ308 with EGF (50 ng/ml for 24 hours) and measure the expression of the five remaining genes by qPCR experiments." (PMID 31438847, 2019).
adenocarcinoma (3 papers, 2014 to 2024). A common cancer characterized by the presence of malignant glandular cells. "In adenocarcinoma histology, the highest expression was of CLCA2 in 13 (62%), followed by survivin in 12 (57.1%) patients." (PMID 39130876, 2024). "In adenocarcinoma histology, the highest expression was of CLCA2 in 62%, followed by survivin in 57.1% of patients." (PMID 39130876, 2024). "Contrary to this, in the present study, CLCA2 was expressed more in adenocarcinoma compared to SCC lung (62% versus 45%) and higher in stage IV in comparison to stage III." (PMID 39130876, 2024). "Studies are underway to determine whether CLCA2 plays a growth-promoting role in those settings, in contrast to its well established anti-proliferative or anti-migratory role in diverse adenocarcinomas." (PMID 29758025, 2018).
CLCA2 also shares sentences with these, for which no sentence is quoted: bladder cancer (1 paper); colorectal cancer (1); esophageal cancer (1); gastric cancer (1); heart disease (1); heart failure (1); ischemia (1); lung squamous cell carcinoma (1); lymphoma (1); metastatic cancer (1); musculoskeletal disorders (1); Obesity (1); pancreatic cancer (1); Premature ovarian insufficiency (1); prostate carcinoma (1); respiratory diseases (1); rheumatoid arthritis (1); squamous intraepithelial lesion (1); triple-negative breast carcinoma (1); type 2 diabetes mellitus (1); urothelial carcinoma (1).